RN7SL636P (RNA, 7SL, cytoplasmic 636, pseudogene)
Gene: Miscellaneous RNA gene on chromosome 20 (50,429,190 to 50,429,483, reverse strand). Ensembl gene ENSG00000244376.
Homologues: Orthologues: chimpanzee Metazoa_SRP (98% identical), macaque Metazoa_SRP (89% identical), dog Metazoa_SRP (61% identical). Paralogues in human: RN7SL1 (85% identical), RN7SL2 (84% identical), RN7SL3 (84% identical), RN7SL45P (81% identical), RN7SL70P (80% identical), RN7SL769P (80% identical), RN7SL126P (80% identical), RN7SL147P (80% identical), RN7SL597P (80% identical), RN7SL91P (80% identical), RN7SL336P (79% identical), RN7SL606P (79% identical), and 705 more.